IDH1 (isocitrate dehydrogenase (NADP(+)) 1)
Diseases named in the same sentence as IDH1 in open-access papers (continued):
Sharing a sentence is not in itself a finding about the gene and the disease.
glioblastoma (continued). "In light of these studies, we interrogated multiple single-cell RNAseq datasets from pediatric diffuse midline gliomas (DMG) and adult IDH1 wild-type glioblastomas (GBM) to curate a list of mechanosensitive ion channels that are expressed in OPC-like cells also expressing CSPG4." (PMID 40791371, 2025). "In the 2021 WHO CNS, glioblastoma is defined as a tumor with obligatory wildtype IDH1/2, characterized by diffuse astrocytic histology and at least one of the following features: necrosis, microvascular proliferation, gain of chr 7 and loss of chr 10, EGFR amplification, or TERT mutation." (PMID 39684714, 2024). "They observed that IDH1-positive glioblastoma patients have a good prognosis." (PMID 39192927, 2024). "Notably, wildtype IDH1 is overexpressed in glioblastoma, an adaptation that supports macromolecular synthesis, aggressive growth and therapy resistance." (PMID 39518074, 2024). "In isocitrate dehydrogenase 1 (IDH1) wildtype glioblastoma, branched chain amino acid transaminase 1 (BCAT1) is also often upregulated and may contribute to a glutamatergic phenotype." (PMID 38835368, 2024). "The median tumor volume was higher in IDH1 mutant glioblastomas (49.8 cm3)." (PMID 39684754, 2024). "It is known that the frequency of IDH1 mutations is lower in classical and mesenchymal subtypes than in proneural and neural subtypes, which is consistent with the recent WHO classification, in which glioblastomas are classified as IDH wild-type." (PMID 39439956, 2024). "While patients with formerly IDH1/2 wildtype tumors WHO grade II and III are younger (45 years), those with WHO grade IV tumors tend to be older (IDH1/2 wt astrocytoma with molecular features of a WHO grade IV tumor: 58 years; IDH1/2 wt glioblastomas: 55 years)." (PMID 39560695, 2024). "Moreover, compared with traditional molecular prognostic markers, e.g., IDH1 mutations, NLR can better evaluate the prognosis of glioblastoma patients and guide the treatment regimen." (PMID 39061427, 2024). "However, it has been shown that the number of oligodendrocytes in IDH1/2 wildtype glioblastoma is much higher than in mutant cases." (PMID 37345193, 2023). "Interestingly, there exists an inverse correlation between IGFBP6 and IDH1 expression in glioblastoma patients." (PMID 35654889, 2023). "The highest mutation frequency of BRAF, ATRX, IDH1, CDKN2A, and EGFR was seen in melanoma (SKCM), thyroid carcinoma (THCA), brain lower-grade glioma (LGG), head and neck squamous cell carcinoma (HNSC), and glioblastoma multiforme (GBM), respectively." (PMID 37000317, 2023). "In patients with glioblastoma, the most aggressive primary brain tumor, the gene encoding BCATc is overexpressed in wildtype but not in isocitrate dehydrogenase 1 (IDH1) mutant type forms." (PMID 36644500, 2023).
glioblastoma (continued). "Glioblastoma is histologically defined as an infiltrating astrocytic glioma with microvascular proliferation or necrosis characterized by a lack of mutations in IDH1, IDH2, and histone H3 genes." (PMID 36831383, 2023). "IDH1 status was available in 47/68 (69.1%) glioblastoma cases." (PMID 37173975, 2023). "Finally, a phase I trial assessing the addition of belinostat to standard-of-care therapy for newly diagnosed glioblastoma patients included one patient with a mutant IDH1 tumor." (PMID 37218937, 2023). "BT1 and BT40 were grade IV glioblastomas with an IDH1 wild-type." (PMID 36835465, 2023). "By carrying out a Pearson correlation analysis between IGFBP6 and IDH1 brain tumor expression levels, we highlighted that in glioblastoma patients, the expression levels of the two genes were significantly closely inversely correlated (r = -0.3743, P < 0.0001)." (PMID 35654889, 2023). "Moreover, the authors further demonstrate a significant increase in the protein expression of BCATc and BCATm in IDH1-WT compared to IDH1-mutant glioblastomas." (PMID 36644500, 2023). "The typical application of radiomics methods in glioblastoma imaging is a differential diagnosis (with other tumors, pseudoprogression), survival prognosis in general life expectancy, identification of molecular biomarkers (for example, IDH1, MGMT)." (PMID 37388754, 2023). "Gross total resection of the tumor revealed IDH-1 wild-type glioblastoma." (PMID 37403078, 2023). "Additionally, it has been found that patients with IDH1-mutant astrocytoma are more prone to experiencing seizures compared with those with glioblastoma." (PMID 38067243, 2023). "Gliomas that harbour an IDH1/2 mutation (IDH-mutant astrocytoma and IDH-mutant and 1p19q-codeleted oligodendroglioma) result in improved patient outcomes as compared to the IDH-wildtype glioblastoma." (PMID 37239289, 2023). "Patients with objective responses in this study had tumors that did not universally harbor the prognostically favorable mutation in IDH1 and had both MGMT methylated and unmethylated tumors, representing the group of glioblastomas that desperately need efficacious therapies." (PMID 37188783, 2023). "A possible explanation for the IDH1 R132H mutation effect on cell culture nanomechanics is that it may be an effect of AVIL protein, which is upregulated in high-grade glioblastoma, especially the IDH1 wild-type." (PMID 36835465, 2023). "Furthermore, SNX10 expression levels negatively correlated with prognosis of glioblastoma patients in TCGA, CGGA and Gravendeel glioblastoma data sets, including in analyses restricted to patients with wild-type IDH1." (PMID 36795488, 2023). "A previous study showed that IDH1 could affect cell migration by modulating the PI3K/AKT/mTOR pathway in primary glioblastoma cells." (PMID 37324278, 2023). "In this study, we analyzed the hippocampal volume in a highly selected group of adult patients newly diagnosed with isocitrate dehydrogenases 1 (IDH1) wild-type glioblastoma, compared to age-matched healthy controls, in order to test hippocampus resilience in brain affected by tumors." (PMID 37178276, 2023). "In a double-blind, placebo-controlled phase 2 study, autologous DC vaccine loaded with glioblastoma-stem-cell-like lines (GSC) prolonged OS in the IDH1-wildtype TERT-mutant and B7-H4 low expression newly-diagnosed GBM patients, with increasing levels of plasma CCL22 and IFN-γ." (PMID 37444531, 2023). "The three tumors harboring IDH1 mutations in this group of 25 glioblastomas did not stand out in any way with respect to cyst fluid concentrations of hormones, serum proteins, electrolytes, or glucose." (PMID 35659255, 2022). "Eighty patients showed glioblastoma (GBM)-like features: IDH1 and 2 wild types (wt) and imbalance of chromosome 7 and chromosome 10q loss of heterozygosity, or telomerase reverse transcriptase (TERT) promoter mutation, or epidermal growth factor receptor (EGFR) amplification." (PMID 36176387, 2022).
glioblastoma (continued). "IDH1 and IDH2 mutations were first found in adult glioblastoma multiforme (GBM) patients." (PMID 35765075, 2022). "A great majority of samples (95%) were primary glioblastomas, while all of them demonstrated the absence of mutation in IDH1 gene." (PMID 35494033, 2022). "Point mutations in the IDH1 or IDH2 gene are correlated with a better overall survival and while they occur frequently in lower-grade astrocytomas (WHO grade II and III) and secondary glioblastomas, they are rare (< 10%) in primary glioblastomas." (PMID 35180887, 2022). "Among 36 patients with butterfly tumor distribution, one patient not meeting the histopathological criteria for glioblastoma and two patients with IDH1 mutation were excluded." (PMID 35892046, 2022). "Isocitrate dehydrogenase 1 (IDH1) and IDH2 mutations are favorable prognostic factors and can facilitate diagnosing astrocytomas and oligodendrogliomas, whereas IDH-wildtype is associated with lower overall survival and characterizes glioblastomas." (PMID 36291914, 2022). "Of note, SLC25A1 inhibition enhanced vulnerability to DNA repair inhibitors of EJ-pathways in irradiated lung and glioblastoma cell line models, without IDH1/2 mutations." (PMID 35869047, 2022). "Targeting IDH1 augmented oxidative stress and reduced glioblastoma growth." (PMID 36153582, 2022). "The prevalence of IDH1 mutation and pMGMT methylation is similar for cystic and non-cystic glioblastomas." (PMID 36605383, 2022). "The comparison III of IDH1-mut versus IDH1-WT glioblastoma revealed several metabolite differences." (PMID 34941573, 2022). "Therefore, the effect of Cyn has been also evaluated on the U-87 MG IDH1 R132H mutant glioblastoma cell line." (PMID 35884887, 2022). "All tumor samples were derived from primary IDH1/2 wild-type glioblastoma samples." (PMID 36132155, 2022). "IDH1 status was available in 28 cases (65%), all of which showed IDH1-wild-type glioblastoma." (PMID 36203443, 2022). "Moreover, H3K27M (A methionine substitution of lysine at residue 27 of histone H3) mutation, regular in pediatric diffuse midline glioma, has also been recognized in malignant adult glioblastoma, with mutual exclusion to IDH1/2 alterations." (PMID 35912242, 2022). "Besides IDH1/2 mutations, the methylation status of the MGMT gene promoter is commonly used in the clinical diagnostic of glioblastoma as a predictive marker of sensitivity to TMZ." (PMID 35884887, 2022). "We tested primary glioblastoma cells from eight patients diagnosed with wild-type IDH1." (PMID 36497392, 2022). "Reported drops in NADPH levels may be a direct result of the NADPH-consuming reaction catalyzed by mutated IDH1, whereas wild-type IDH1 was identified as the main source of cytosolic NADPH in glia cells and glioblastoma." (PMID 35628596, 2022). "Mutations in IDH1 reduce IDH1’s catalytic activity and activate HIF-1 α in glioblastoma cells." (PMID 35924146, 2022). "As expected, an analysis of the distribution of nonsynonymous mutations showed that the TMB-high group had a higher incidence of mutations typical for glioblastoma (PTEN: 29% vs. 5%; EGFR: 17% vs. 5%), while the opposite was true for mutations associated with low-grade gliomas (IDH1: 77% vs. 7%)." (PMID 35406398, 2022). "IDH1 wild-type glioblastoma (GBM) is the most common and malignant among gliomas." (PMID 35414102, 2022). "Since current WHO guidelines define the wildtype IDH1 locus as a defining mark to diagnose the neoplasm as glioblastoma, our data supports elevated Lyn mRNA abundancy as a compliment marker indicative for glioblastoma." (PMID 35628503, 2022). "We detected higher hypotaurine levels but reduced ADO gene expression in IDH1-WT glioblastoma." (PMID 34941573, 2022).
glioblastoma (continued). "In comparison VI (n = 7 IDH1-mut glioblastoma versus n = 29 IDH1-mut oligodendroglioma), we found 19 significant metabolites in the 2-tailed t test, including sarcosine, glutamate, taurine, AMP, uridine, phenylalanine, lactate, glutathione, formate, and citrate." (PMID 34941573, 2022). "Glioblastoma [idh-1 (r132h) mutant] - who grade iv; right frontal." (PMID 34630267, 2021). "While the tryptophan metabolism pathway is by far the most clinically explored in IDH1 wildtype glioblastoma with 2 studies completed (NCT02052648, NCT02502708) and two studies recruiting (NCT04047706, NCT04049669), other pathways have unfortunately been less pursued." (PMID 34222022, 2021). "Nine cases had glioblastomas-IDH1-wild and one case had glioblastoma-IDH1-mutant." (PMID 34603572, 2021). "Moreover, we will delve deeper into genotyping our model for numerous interests, including CDKN2A deletion, EGFR amplification, IDH1/2, FGFR-TACC3, and H3K27M mutation because of their prevalence in human glioblastoma." (PMID 34884748, 2021). "IDH1 was also identified as a favorable prognostic factor for glioblastoma." (PMID 34606414, 2021). "Specifically, BCAT1 expression is dependent on the concentration of α-ketoglutarate (α-KG) substrate and could be suppressed by downregulation of IDH1 in glioblastoma cell lines or overexpression of mutant IDH1 in immortalized human astrocytes." (PMID 33493139, 2021). "Although IDH1-mutant glioblastomas showed late tumor recurrence in patients less than 50 years old, the type of treatment modalities may not show additional beneficial outcome." (PMID 34257620, 2021). "Although IDH1 mutant glioblastomas showed late tumor recurrence in patients younger than 50 years of age, the type of treatment modalities may not show additional beneficial outcome." (PMID 34257620, 2021). "Additionally, consistent with previous studies, miR-411, as well as KPS and IDH1, was revealed to function as an independent prognostic indicator for glioblastoma." (PMID 34606414, 2021). "However, in this study, similar to SUV analysis, even fractal analysis was unable to distinguish between IDH1-wildtype diffuse astrocytoma and anaplastic astrocytoma and glioblastoma." (PMID 34743250, 2021). "Relationship between IDH1 mutation and MGMT promoter methylation in glioblastoma patients." (PMID 34257620, 2021). "Furthermore, when asked about the use of routine IDH1 analysis for pediatric anaplastic astrocytoma and glioblastoma, only very high HDI countries considered this obligatory." (PMID 34595479, 2021). "Glioblastomas of the donors of GSCs_a and GSCs_c revealed no mutation for the isocitrate dehydrogenase (NADP(+)) 1 (IDH1), whereas in the glioblastoma of the donor of GSCs_b IDH1 was mutated." (PMID 33800955, 2021). "However, they were able to study this effect in glioblastomas, and they observed that IDH1-mutant tumors were on average stiffer than IDH1-wildtype ones." (PMID 34572766, 2021). "One-hundred sixty-five patients had a IDH1 wild-type glioblastoma." (PMID 34178693, 2021). "Mutations in IDH1 appear to preferentially occur in younger glioblastoma patients (mean age: 33 or 41 years) as opposed to wild-type carriers (mean age: 53 or 56 years) and are mostly detected in patients with secondary GBM." (PMID 33673213, 2021). "The aim of this study is to investigate the relationship between isocitrate dehydrogenase-1 (IDH1) mutation and O6-methylguanine-DNA methyltransferase (MGMT) promoter methylation with recurrence-free interval in glioblastoma patients treated with chemoradiotherapies." (PMID 34257620, 2021).
glioblastoma (continued). "Hence, the study was limited for TRIP13 expression analysis in primary glioblastoma to explore the relationship with IDH1." (PMID 34066132, 2021). "In IDH1-wildtype glioblastoma cases treated with chemoradiotherapy showed 57.6% recurrence free in the 12th month, which is relatively higher than what was observed in IDH1-wildtype cases that received only radiation (35.3%), however; slightly opposite behavior was observed at 2 years." (PMID 34257620, 2021). "However, the U87IDHmut model is genetically engineered to express mutant IDH1 in U87 glioblastoma cells." (PMID 33668509, 2021). "A previous study showed that the growth of glioblastomas (mostly IDH1 wild-type) from small to large tumors could take as short as 1.5 months." (PMID 34631582, 2021). "Most of these glioblastomas were supratentorial (frontoparietal area), IDH1 wild-type, MGMT non-methylated, and associated with poor outcomes and a high recurrence rate." (PMID 34030435, 2021). "We tried to figure out the best culture condition for glioblastoma with IDH1 mutation and LGG with/without 1p19q co-deletion, previously known as hard to grow and easily eliminated in standard NBE culture conditions." (PMID 32120790, 2020). "Nevertheless, constitutively active HIF was observed in glioblastomas with mutant IDH1, and it has been hypothesized that the activity of PHD2 is inhibited by 2HG." (PMID 31847543, 2020). "Interestingly, gene-set enrichment analysis (GSEA) revealed that genes related to cell proliferation were enriched in E&F-dependent IDH1-wt glioblastoma GSCs, while genes related to a mesenchymal subtype signature were enriched in the E&F-independent group." (PMID 32120790, 2020). "MGG119, MGG152, BT142 primary glioblastoma cell lines; HT1080, 30T and SW1353 chondrosarcoma cell lines; SNU484, SNU668, SNU1750, MKN1 and Hs746T gastric cancer cell lines which have mutations in IDH1, were sensitive to NAMPT inhibition." (PMID 32111066, 2020). "The heterogeneity of IDH1/2 wild-type glioblastoma limits its prognosis and therapy." (PMID 32620753, 2020). "The overexpression of IDH1 is required to tumor growth in glioblastoma, it could catalyze the conversion of isocitrate and NADP+ to 2-oxoglutarate and NADPH." (PMID 32784466, 2020). "Isocitrate dehydrogenases (IDH1/2) are central molecular markers for glioblastoma." (PMID 33221817, 2020). "In our cohort, all LGGs (n = 19) and six out of 53 (11.3%) of the glioblastomas harbored IDH1 mutations; among the LGGs, nine (47.4%) showed 1p19q co-deletion, while no samples showed 1p19q co-deletion in glioblastomas." (PMID 32120790, 2020). "In both the CGGA (all grades, n = 297) and TCGA (glioblastoma, n = 418) array datasets, patients with strong EFEMP2 expression were primarily harboring wild type IDH1, whereas most of the ones with low EFEMP2 expression harbored IDH1 mutation." (PMID 32396873, 2020). "A comparison of features that were selected by XGBoost and analysis of features with statistically significant differences between IDH1 wildtype and mutants (Table A1) and between glioblastomas and non-glioblastomas (Table A2) shows the effectiveness of the automated feature selection." (PMID 33121211, 2020).